PPARG (peroxisome proliferator activated receptor gamma)
Diseases named in the same sentence as PPARG in open-access papers (continued):
Sharing a sentence is not in itself a finding about the gene and the disease.
injury (29 papers, 2013 to 2025). Damage inflicted on the body as the direct or indirect result of an external force, with or without disruption of structural continuity. "Phosphorylation of PPARγ at Ser112 was recently shown to be mediated by the upstream JNK-MAPK in a murine acute lung injury model." (PMID 36928191, 2023). "Consistent with the current findings, Zhang showed that Klotho levels can be affected by PPARγ activation in a mouse model of traumatic brain injury." (PMID 36556233, 2022). "To clarify the effect of PPARγ on Egr-1 expression in vivo, we first examine the production of Egr-1 during IgG-IC-induced acute lung injury." (PMID 33717177, 2021). "Previous studies have reported antinociceptive effects of the PPARγ agonist pioglitazone in models of nerve injury induced neuropathy." (PMID 25759824, 2015). "In summary, 15d-PGJ2 reduces the release of proinflammatory cytokines in ConA-induced acute liver injury by blocking the activation of NF-κB, and the activation of PPARγ by 15d-PGJ2 participates in this process." (PMID 25120564, 2014). "Furthermore, IL-4 treatment failed to enhance oligodendrogenesis and differentiation in oligodendroglial PPARγ conditional knockout mice after ischemic and traumatic brain injury." (PMID 41294810, 2025). "Therefore, PPARγ activation might represent a promising therapeutic option for IgG-IC-induced acute lung injury." (PMID 33717177, 2021). "Apoptotic cell alone was reported to increase efferocytic activity via the induction of PPARγ and CD36 in bleomycin induced lung injury mouse model." (PMID 32274896, 2020). "Thus, persistently enhanced PPARγ activity following in vivo exposure to apoptotic cells might strengthen apoptotic cell recognition and clearance system and prevent a defect in the ability of macrophages to clear them during bleomycin-induced lung injury." (PMID 28594406, 2017). "There is a certain relationship between the activation of peroxisome proliferator-activated receptor gamma (PPAR-γ) and anti-inflammatory neuroprotective effects in various acute and chronic central nervous system (CNS) diseases (spinal cord injury, focal cerebral ischemia, etc.)." (PMID 36389255, 2022).
leukemia (29 papers, 2006 to 2025). A malignant (clonal) hematologic disorder, involving hematopoietic stem cells and characterized by the presence of primitive or atypical myeloid or lymphoid cells in the bone marrow and the blood. "A PPARγ agonist induced marrow adipogenesis, and this rescued normal progenitor outgrowth while suppressing leukemia growth." (PMID 31492897, 2020). "The combination of ATRA and As2O3 enhanced PPARγ expression in leukemia cells from APL patients after 1 week of induction therapy." (PMID 32929351, 2020). "To determine how PML-RARα is involved in the metabolic disorders associated with APL, we examined the expression of PM-RARα and PPARγ in leukemia cells from APL patients." (PMID 32929351, 2020). "T0070907 has been used to reduce peroxisome proliferator-activated receptor gamma (PPAR-γ) expression in lipopolysaccharide (LPS)-induced leukemia RAW264.7 cell line, therefore it is PPAR-γ specific inhibitor." (PMID 31562809, 2019). "In vivo, administration of PPARγ agonists additionally induced BM adipogenesis, which rescued healthy hematopoietic maturation while repressing leukemia growth." (PMID 30542286, 2018). "Studies in leukemia suggested that PPARγ regulates apoptosis at the level of caspase 8, and its coactivator DRIP205 was found to promote cell differentiation via PPARγ." (PMID 22654896, 2012). "In patients, PPARγ protein is expressed (in varyinglevels) in leukemias, lipo- and osteosarcomas and in many carcinomas." (PMID 18596912, 2008). "For example, activation of PPARγ can inhibit leukemia stem cells by suppressing STAT5 expression." (PMID 36147468, 2022). "A new therapeutic option could involve a combination of imatinib and chemical compounds capable of exerting antiproliferative effects against K562-resistant leukaemia cells via PPARγ activation." (PMID 33053860, 2020). "Moreover, the lipid levels of mice transplanted with PPARγ-depleted leukemia cells were much higher than those of control mice." (PMID 32929351, 2020). "Peroxisome proliferator-activated receptor-γ (PPARG), is expressed in a large number of human cancers, including breast, colon, stomach, prostate, pancreas, bladder, placenta, lung, chondrosarcoma and in leukemia." (PMID 21059268, 2010). "PPARγ is expressed in a variety of immune cells as well as in numerous leukemias and lymphomas." (PMID 18528522, 2008). "However, our data on single cell colonies suggest that a subpopulation of committed osteoprogenitors or relatively mature osteoblasts is also induced to switch on the adipogenic pathway (pathway 3) when PPARγ is activated, as we also recently proposed with leukemia inhibitory factor treatments." (PMID 18625072, 2008). "In leukemia, LGALS1 upregulates the expression of genes involved in lipid uptake (such as CD36) and de novo lipogenesis (such as PPARγ, FASN, and ACC), thereby enhancing lipid accumulation." (PMID 40881692, 2025). "It was also found in leukemia cells that non-coding variants at KRAS and PER2 enhancers affect the binding of nuclear receptor family TFs PPARG and RXRA, which disturbs the expression of KRAS and PER2 and promotes the growth of leukemia cells." (PMID 39724337, 2025). "Another regulatory link identified as an important discriminator between the two types of leukemia, with a score just below this cutoff, involves the C/EBP alpha (CCAAT/enhancer binding protein, CEBPA) regulating PPAR-gamma (PPARG)." (PMID 16670008, 2006). "We first performed oligoprecipitation experiments in a monocytic leukemia cell line, THP-1, and both endogenously expressed PPARγ and STAT6 could be pulled down with wild-type MacPPRE." (PMID 21093321, 2010). "To test whether this effect was PPAR-dependent, we measured proliferation of the haploid human leukemia cell line HAP1, and genetically engineered versions that lack functional proteins PPARα (HAP1 PPARA KO) or PPARγ (HAP1 PPARG KO), after adding arachidonic acid." (PMID 34984327, 2022).
leukemia (continued). "Proliferation of normal BMAT induced by PPARγ agonists could rescue healthy hematopoiesis and repress leukemia development, indicating that targeting BMAT could be regarded as a potential strategy to arrest leukemia progression." (PMID 34246314, 2021). "Similarly, increases in serum TG and TC levels were observed in mice transplanted with PPARγ-depleted leukemia cells but not in mice transplanted with control leukemia cells." (PMID 32929351, 2020). "However,a study using a large number of human tumor samples and cell lines (n = 397),including those from leukemias, found no detectable abnormalities, either inPPARγ exon 3 (DBD) or in exon 5 (LBD),suggesting that PPARγ gene mutations may occur, but are rare." (PMID 18528522, 2008). "Our study reveals that PPARγ activation reduces the phosphorylation of STAT5 but not its expression, which is essential for leukemia cell survival." (PMID 39696470, 2024). "Leukemia cells from most APL patients showed reduced PPARγ protein expression and enhanced resistin and TRIB3 protein levels compared with those in leukemia cells from non-APL patients." (PMID 32929351, 2020).
breast tumor (28 papers, 2007 to 2025). "In summary, the reduction in CD36 expression observed in the vasculature surrounding premalignant lesions and fully invasive breast tumors coincided with a loss of PPARγ expression within the vasculature." (PMID 37816052, 2023). "PPARγ is also expressed in several cells of the breast tumor microenvironment, among which tumor associated macrophages (TAMs) play a pivotal role in tumor progression and metastasis." (PMID 31936729, 2020). "Compared to DMBA Only-treated PPARγ-WTs, both breast tumour susceptibility and serum levels of proinflammatory and chemotactic cytokines, namely IL-4, eotaxin, GM-CSF, IFN-γ, and MIP-1α, were decreased among PPARγ-MG KOs." (PMID 25889730, 2015). "Surprisingly, it was discovered that PPARγ-MG KO mice are protected more so than PPARγ-WTs during DMBA-mediated breast tumourigenesis; whereas, PPARγ activation by ROSI rescues PPARγ-WTs but renders PPARγ-MG KOs more susceptible to breast tumour progression." (PMID 25889730, 2015). "Protein expression of PPARG was detected at low levels in both normal breast and breast tumor tissues." (PMID 36114448, 2022). "Despite significant knowledge on the role of PPARγ as a breast tumor suppressor in basic science, translation of these findings into human clinical trials has provided few encouraging results and needs to be further investigated." (PMID 34067944, 2021). "It is worth pointing out that in this study, a decreased nuclear PPARγ expression was detected in the breast tumor tissue of patients treated with rosiglitazone, suggesting the rosiglitazone-mediated effects on breast cancer cell signaling." (PMID 34067944, 2021). "When we used as keywords “PPARγ” and “tumor microenvironment”, only 104 papers were published from 2002 to 2020 which were restricted to 19 results with the terms “PPARγ” and “breast tumor microenvironment” from 2008 to 2020." (PMID 33352766, 2020). "Activation of the apoptosis-related peroxisome proliferator-activated receptor-gamma (PPAR-γ) pathway induced a synergistic effect on breast tumor cells." (PMID 33006013, 2020). "Previously, we showed, using 7,12-dimethylbenz [a] anthracene (DMBA)-treated haploinsufficient PPARγ mice, that PPARγ suppresses breast tumour progression; however, the PPARγ expressing cell types and mechanisms involved remain to be clarified." (PMID 25889730, 2015). "Here we provide the first in vivo evidence that PPARγ activation in MG cells blocks breast tumour progression in PPARγ-WTs by upregulating BRCA1, and downregulating VEGF and Cox-2, expression." (PMID 25889730, 2015). "A breast tumour suppressor role for PPARγ was first demonstrated in vitro when treatment of human MCF-7 and MDA-MB-231 breast cancer cells with PPARγ ligands resulted in decreased cell proliferation, promotion of differentiation, and induction of apoptosis." (PMID 25889730, 2015). "Here we unveil evidence that MG-specific PPARγ expression enhances early breast tumour events; whereas, more importantly activation of MG-specific PPARγ-dependent signaling reduces breast tumour progression." (PMID 25889730, 2015). "We previously showed that mammary adipocyte-specific PPARγ blocks breast tumour progression in part via upregulation of BRCA1." (PMID 25889730, 2015). "This study provides insight into the MG cell-specific role of PPARγ during DMBA-mediated breast tumour progression." (PMID 25889730, 2015). "It has been observed that while PPARγ agonists inhibit growth and induce apoptosis in both breast tumor cells and leukemic cells, administration of PPARγ antagonists enhanced this tumor growth inhibitory effect." (PMID 20182546, 2010). "In an analysis of primary breast tumors, PPARγ expression was more often in low-grade than high-grade tumors, associated with a more favorable survival, and decreased in tumor relapses." (PMID 20182546, 2010).
breast tumor (continued). "Similarly, the GSE114082 dataset suggests a significant increase in PPARG expression levels in HER2-positive breast tumors following treatment with trastuzumab." (PMID 40303293, 2025). "The expression of PPARG was upregulated in lung, prostate, colorectal, bladder, and breast tumors." (PMID 35069936, 2022). "Interestingly, we also highlighted the in vivo ability of activated PPARγ to antagonize the breast tumor growth induced by leptin in nude mice." (PMID 34067944, 2021). "Furthermore, ligand-activated PPARγ in the surrounding stromal components creates a milieu that hinders breast tumor progression." (PMID 33352766, 2020). "In the breast tumor microenvironment, several cells, including TAMs, express PPARγ." (PMID 31936729, 2020). "Thus, we focused on the molecular mechanism by which PPARγ mediates the inhibition of CXCR4 expression in breast tumor cells." (PMID 27556298, 2016). "There are indeed reports that PPARγ levels decline as human breast tissue becomes increasingly malignant, which is consistent with our hypothesis of its role as a suppressor of breast tumour progression." (PMID 25889730, 2015). "This suggests activation of PPARγ may protect against breast tumour progression only when mammary epithelial-stromal crosstalk contains functional PPARγ signaling in both cell types, and is the focus of additional studies beyond the scope of this work." (PMID 25889730, 2015). "The results suggest PPARγ signaling in MG cells may be required during early mammary tumourigenesis; however, activation of PPARγ within this cell population is protective against the growth and spread of breast tumours." (PMID 25889730, 2015). "In addition, overexpression of a constitutive active form of PPARγ promoted breast tumor development." (PMID 21144036, 2010). "In addition, evaluation of the expression level of PPARγ and its subcellular localization in early-stage breast tumors should be considered a tailored selection criteria for patients to develop more effective translational and precision medicine strategies for breast cancer patients." (PMID 34067944, 2021). "We now understand that PPARγ is expressed and functions not only in epithelial breast cancer cells but also in other components of the breast TME, including cancer-associated fibroblasts (CAFs) and tumor-associated macrophages (TAMs) interfering with breast tumor progression." (PMID 34067944, 2021). "Unraveling the precise role of PPARγ in the complex tissue response in cancer could be paramount for a rational design of new therapy schemes that take advantage of the potent antitumor action of PPARγ agonists targeting both epithelial and stromal cells within a breast tumor microenvironment." (PMID 33352766, 2020). "More interestingly, synthetic and natural PPARγ agonists significantly reduced the production of the cytokine IL1Ra, simultaneously attenuating both M1 and M2 macrophage phenotypes, which are known to promote a pro-tumorigenic milieu in the breast tumor microenvironment." (PMID 31936729, 2020). "Moreover, activated PPARγ may cross-talk with other signal transduction pathways antagonizing breast tumor proliferation." (PMID 32937951, 2020). "Cotreatment with a gold standard PPARγ activator, ROSI, further provided the ability to identify PPARγ-dependent anti-breast tumour progression signaling pathways specific to MG cells." (PMID 25889730, 2015). "Moreover, one of the future priorities for a rational use of PPARγ agonists will be the identification of the subgroups of breast tumors currently lacking effective therapeutic options, which may really benefit from novel adjuvant therapeutic interventions." (PMID 32937951, 2020). "Interestingly, our data showed that CAFs exposed to the treatment with the PPARγ agonist BRL acquired a phenotype characterized by a decreased expression of α-SMA/vimentin and CXCR4 together with a reduced migratory capability, all features that may negatively impact breast tumor progression." (PMID 27556298, 2016).
breast tumor (continued). "Collectively, these findings suggest that PPARγ expression in MG cells and ROSI activation in mice lacking MG-specific PPARγ is potentially harmful during chemical-mediated breast tumour progression." (PMID 25889730, 2015).
preeclampsia (28 papers, 2008 to 2025). Preeclampsia is a hypertensive disorder of pregnancy that is characterized by new-onset hypertension with proteinuria presenting after 20 weeks of gestation, and depending on mild or severe forms may initially present with severe headache, visual disturbances, and hyperreflexia. "Previous reports have shown that the transcription factor PPARγ is essential for placental development and alterations in its expression and/or activity are associated with human placental pathologies such as preeclampsia." (PMID 38003549, 2023). "Peroxisome proliferator-activated receptor γ (PPARγ) is essential for placental development, whose SNPs have shown increased susceptibility to pregnancy-related diseases, such as preeclampsia." (PMID 34685423, 2021). "In the present study, we identify a significant association between the C1431T SNP of PPARγ and preeclampsia." (PMID 34685423, 2021). "Our aim was to investigate the association between preeclampsia and three PPARγ SNPs (Pro12Ala, C1431T, and C681G), which together with nine clinical factors were used to build a pragmatic model for preeclampsia prediction." (PMID 34685423, 2021). "In the current study, we aimed to investigate the association between the risk of preeclampsia and the Pro12Ala, C1431T, and C681G SNPs of PPARγ." (PMID 34685423, 2021). "Even though multiple studies have suggested that SNPs in various genes increase the risk of preeclampsia, the association between SNPs of PPARγ and the risk of preeclampsia has been poorly investigated." (PMID 34685423, 2021). "This final decision tree showed that the C1431T variant of PPARγ is significantly associated with susceptibility to preeclampsia." (PMID 34685423, 2021). "Inhibition of PPARγ during pregnancy in rats with the ligand inhibitor T0070907 caused key features of preeclampsia to develop, including elevated mean arterial pressure, proteinuria, systemic endothelial dysfunction, and reduced fetal weight." (PMID 23888144, 2013). "Recent data indicate that circulating activators of PPARγ are reduced in human pregnancy complicated with preeclampsia that is often associated with intrauterine growth restriction (IUGR)." (PMID 23888144, 2013). "Given that SNPs in the PPARγ gene have been implicated in a wide range of diseases, we hypothesized that such variants may also play a role in preeclampsia." (PMID 34685423, 2021). "There is compelling evidence to suggest an association between PPARγ and preeclampsia." (PMID 23888144, 2013). "In addition, women with Pro467Leu mutation, a dominant negative mutation of PPARγ, had pregnancies complicated with gestational diabetes and severe preeclampsia." (PMID 23888144, 2013). "This can cause a strongtransactivation of PPARγ during early pregnancy, resultingin a reduction of extravillous trophoblastic invasion, one cellular explanationoften cited in the physiopathology of preeclampsia." (PMID 18288292, 2008). "However, in spite of the well-documented function of PPARγ in placental development and its association with preeclampsia, expression of these receptors and their role in the control of uteroplacental blood flow during pregnancy remains unknown." (PMID 23888144, 2013). "Although TFPI2 overexpression in placental tissue is thought to enhance PPARγ levels, PPARγ expression is paradoxically diminished in gestational hypertension, contributing to an exacerbated inflammatory milieu." (PMID 40361374, 2025). "The study aims to explore the effect of PPARγ signaling on ferroptosis and preeclampsia (PE) development." (PMID 38594496, 2024). "Therapeutic interventions targeting factors such as peroxisome proliferator-activated receptor gamma (PPAR-γ) and endothelin receptors show potential in mitigating preeclampsia-related complications." (PMID 38674114, 2024). "In humans, PPARg levels increase during normal gestation and unaltered in preeclampsia, although incubating trophoblasts with serum from preeclamptic women did upregulate PPARg." (PMID 36698175, 2023).